MMP7 (matrix metallopeptidase 7)
Diseases named in the same sentence as MMP7 in open-access papers (continued):
Sharing a sentence is not in itself a finding about the gene and the disease.
ovarian carcinoma (continued). "In addition, various malignancy levels of Matrilysin are also expressed and studies identified the relation of MMP-7 with ovarian cancer and its metastasis." (PMID 31583159, 2019). "Previously, we reported that a four-biomarker panel comprising CA125, HE4, CA72-4 and MMP-7 showed strong diagnostic performance and significant improvement over the use of CA125 alone in distinguishing patients with early stage ovarian cancer from healthy women." (PMID 31035430, 2019). "In addition, MMP-7 also promotes the invasion and metastasis of ovarian cancer through MSLN-activated MAPK/ERK and JNK pathways." (PMID 29393911, 2018). "Moreover, MMP-7 promotes the invasion and metastasis of ovarian cancer cells by activating gelatin enzyme." (PMID 28538838, 2017). "The systematic review on 12 polymorphisms suggested that MMP2 C-735T, MMP7 A-181G, MMP8 rs11225395, MMP9 rs6094237, MMP12 rs2276109, MMP20 rs2292730, MMP20 rs12278250, MMP20 rs9787933 might have a potential effect on ovarian cancer risk." (PMID 28957437, 2017). "Triptolide inhibits the migration and invasion of ovarian cancer cells by suppression of MMP-7." (PMID 28538838, 2017). "We found comparable results regarding MMP-7 in the ovarian cancer." (PMID 28662671, 2017). "Similarly, placental growth factor (PLGF) suppresses miR-543 and miR-543 which inhibits MMP7 translation, therefore high levels of PLGF as seen in ovarian cancer specimens increase MMP7 levels and thus the cancer’s invasion ability." (PMID 27231010, 2016). "Besides these limitations, the serum estimation of MMP7 could give us an insight into the expression of this gene and further substantiate the role of MMP7 in ovarian cancer." (PMID 38638796, 2024). "Moreover, MMP-7 was reported to be a malignant biomarker in ovarian cancer." (PMID 36518899, 2022). "The presence of MMP-7, MMP-26, MMP-3, MMP-10, and MMP-11 expression has been previously confirmed in biopsy material from ovarian cancer patients." (PMID 41007705, 2025). "Ovarian cancer cells (Ovcar3) treated with an activator of the PKC pathway, phorbol-12-myristate 13-acetate (PMA), increased MMP7 and MMP10 mRNA." (PMID 40558552, 2025). "Most of the tested metalloproteinases upregulated mRNA expression in both FIGO I/II and FIGO III/IV stages of ovarian cancer (MMP1, MMP13, MMP2, MMP9, MMP10, MMP7, MMP12 and MMP14) indicating profound modifications of the extracellular matrix." (PMID 38397798, 2024). "MSLN promotes the expression of matrix metalloproteinase-7 (MMP-7) through the MAPK/ERK and JNK signaling pathways, thereby enhancing the migration and invasion of ovarian cancer cells." (PMID 39023820, 2024). "The increased expression and activity of MMP7 and MMP9 create conditions favorable for the metastasis of ovarian cancer cells by remodeling the extracellular matrix, enhancing their migration, and facilitating attachment to secondary sites." (PMID 37569592, 2023). "Exogenous treatment of leptin in SKOV3 and OVCAR3 ovarian cancer cells resulted in the activation of EKR1/2 and JNK1/2 and induced expression of MMP-7, -2, and -9, which are factors known to induce migration." (PMID 35565396, 2022). "In particular, EpCAM-MC is a personalized APEC-immunotherapy for ovarian cancer that cleaves a CMV peptide (NLVPMVATV; abbreviated NLV) by tumor-expressed MMP7 and then is presented by MHCI (HLA-A*02:01)." (PMID 34415995, 2021). "The role of VEGF-VEGFR in invasion and migration of ovarian cancer is proven in vitro through the secretion and activation of Matrix Metalloproteinase-2 (MMP-2), MMP-7, MMP-9 and urokinase type plasminogen activators." (PMID 33639643, 2021). "MMP-2, MMP-3, MMP-7, and MMP-9 are thought to be involved in the invasion and migration of tumor cells in ovarian cancer." (PMID 31035447, 2019). "Until now, well known MMPs which levels correlate with ovarian cancer are levels of MMP2, MMP7 and MMP9." (PMID 29304854, 2018).
ovarian carcinoma (continued). "VEGF regulates ovarian cancer invasion and migration in vitro through VEGFR-mediated secretion and activation of MMP-2, MMP-7, and MMP-9." (PMID 28476025, 2017). "MMPs are correlated with ovarian cancer, with the levels of MMP-2, MMP-7 and MMP-9 elevated in ovarian cancer patients." (PMID 28957437, 2017). "A maximum range of NPV (98–100%) was obtained for the combination of MMP-7 with HE4 and/or CA125 in stages III-IV of ovarian cancer." (PMID 28662671, 2017). "Our results showed that MMP-2, MMP-7, MMP-9 and MMP-10 expression were significantly up-regulated in ovarian cancer tissue compared with normal ovarian tissues." (PMID 28476165, 2017). "Several studies have confirmed this observation - they found sensitivity to be greater than in either marker used alone: MMP-7, CCL18 (CC chemokine 18), CCL11 (CC chemokine 11) and CA125 in ovarian cancer (SE in the early stages 94.4%)." (PMID 28662671, 2017). "Some studies have been published on the prognostic value of MMP2, MMP7 and TIMP2 in ovarian cancers, but it is still controversial." (PMID 27835587, 2016). "Other serum markers, which include mesothelin, matrix metalloproteinase 7 (MMP7), cytokeratin 19 fragment (CYFRA 21-1), and glycodelin, have shown encouraging performance in ovarian cancer, but mainly in clinical series." (PMID 26819954, 2015). "Markers such as IGFII, IL-13rα, MIP1α and MMP-7 correlated well with high amount of plasma sEPCR and CA125 in ovarian cancer." (PMID 23877403, 2013). "We therefore, used a translational approach to analyze the epithelial and stromal expressions of MMP-2, MMP-7, MMP-9, MT1-MMP, TIMP-1 and TIMP-2 in advanced epithelial ovarian cancers and to assess their prognostic value." (PMID 22200690, 2012). "About 15 studies have been published on the prognostic value of MMP-2, MMP-7, MMP-9, MT1-MMP, TIMP-1 or TIMP-2 in ovarian cancers, but the results remain controversial." (PMID 22200690, 2012). "We set out to analyze the epithelial and stromal expression of MMP-2, MMP-7, MMP-9, MT1-MMP, TIMP-1 and TIMP-2 in advanced epithelial ovarian cancers and to assess their prognostic value." (PMID 22200690, 2012). "Moreover, only the expressions of MMP7, MMP12, TIMP3, CAT and Nrf2 were affected by the clinical stage of ovarian cancer." (PMID 38397798, 2024). "By comparing ovarian cancer tissues with distant non-ovarian cancer tissues in ovarian cancer patients, MMP-7 was significantly increased in ovarian cancer tissues, and miR-543 was significantly reduced." (PMID 31035447, 2019). "Four biomarkers with significant relevance to ovarian cancer including carbohydrate antigen 125 (CA125), human epididymis protein 4 (HE4), matrix metalloproteinase-7 (MMP-7) and Cancer Antigen 72-4 (CA72-4) were tested with this device using serum and plasma samples." (PMID 29258216, 2017). "Targeted inhibition of MMP-7 and MMP-10 may provide potential ovarian cancer therapeutic strategy." (PMID 28538838, 2017). "The aim of this study was to investigate whether other ovarian cancer-related biomarkers, Human Epididymis 4 (HE4), glycodelin, mesothelin, matrix metalloproteinase 7 (MMP7), and cytokeratin 19 fragment (CYFRA 21-1), could improve the performance of CA125 in detecting ovarian cancer earlier." (PMID 26819954, 2015). "Eight polymorphisms (MMP2 C-735T, MMP7 A-181G, MMP8 rs11225395, MMP9 rs6094237, MMP12 rs2276109, MMP20 rs2292730, MMP20 rs12278250, MMP20 rs9787933) were reported associated with ovarian cancer risk, while other polymorphisms could not be associated with ovarian cancer risk." (PMID 28957437, 2017). "This work also supports previous studies showing the potential of HE4, whilst suggesting that mesothelin, MMP7, and CYFRA 21-1 are not useful markers for the early detection of ovarian cancer." (PMID 26819954, 2015).
prostate carcinoma (59 papers, 2002 to 2025). A carcinoma that arises from epithelial cells of the prostate gland. "PKP3 functions in the tumor microenvironment of prostate cancer, regulating invasion of the cell and development of the tumor through the MMP7 protein, and is associated with poor patient prognosis." (PMID 37760912, 2023). "In a MMP-7-deficient prostate cancer model, it is observed that MMP-7-deficient treatment reduces the risk of osteolytic bone metastasis as a result of aberrations in RANKL processing." (PMID 35386705, 2022). "In accordance, we previously found in two independent patient cohorts of bladder and prostate cancer that high soluble serum SDC1 levels are directly associated with elevated MMP-7 serum levels, which suggests MMP-7 as a major protease for SDC1 shedding." (PMID 33114033, 2020). "The association of perlecan fragments in sera and MMP-7 expression in tissues reflects prostate cancer invasivity." (PMID 32351878, 2020). "We found high pretreatment MMP-7 serum levels to be independently associated with poor response and shorter OS of castration-resistant prostate cancer patients who received docetaxel chemotherapy." (PMID 33396213, 2020). "The polymorphism rs11568818 in MMP-7 gene was also associated with an increased prostate cancer risk in Poland." (PMID 30036379, 2018). "The increased transcription of MMP-7 was also associated with development and progression of prostate cancer in human both in vitro and in vivo." (PMID 30036379, 2018). "Analyses of polymorphisms in genes encoding Zn-associated proteins revealed a significant correlation of rs11568818 in MMP-7 gene with an increased prostate cancer risk." (PMID 30036379, 2018). "Among five analyzed genetic variants, rs11568818 in MMP-7 appeared to be correlated with 2-fold increased prostate cancer risk (OR = 2.39, 95% CI = 1.19–4.82, p = 0.015)." (PMID 30036379, 2018). "One of the analyzed polymorphisms, rs11568818 in MMP-7, was also associated with increased prostate cancer risk (p = 0.03)." (PMID 30036379, 2018). "Among the five analyzed genetic variations one polymorphism (rs11568818) in MMP-7 appeared to be correlated with prostate cancer risk." (PMID 30036379, 2018). "By combining a murine model of myeloma with MMP-7 deficient mice, our results suggest that, in contrast to breast and prostate cancer bone metastasis, a loss of host-derived MMP-7 increases tumor growth and osteolytic bone disease." (PMID 28241871, 2017). "MMPs have been implicated in these interactions, in particular MMP-7, which has previously been shown to be highly expressed within the tumor-bone microenvironment and to promote breast and prostate cancer osteolysis in vivo." (PMID 28241871, 2017). "In a study investigating the serum levels of various MMPs in relation to the invasiveness of the prostate cancer, high circulating serum MMP-7 was associated with prostate cancer distant metastases, but the prognostic role of MMP-7 is not clear." (PMID 24978435, 2014). "We found significant association of rs11568818 in MMP-7 gene with higher prostate cancer risk." (PMID 30036379, 2018). "Moreover, genotyping of rs11568818 in MMP-7 could identify those patients who have an increased risk of developing prostate cancer in the Polish population." (PMID 30036379, 2018). "For example, MMP7 promoted epithelial-mesenchymal transition of prostate cancer by promoting IL-17 expression." (PMID 38526326, 2024). "Of these, three protein associations with risk of prostate cancer overall were replicated in men of African ancestry: MSMB [OROverall = 0.85, 95% CI: 0.80–0.91], MMP7 [OROverall = 0.83, 95% CI: 0.73–0.95], and ISLR2 [OROverall = 0.85, 95% CI: 0.73–0.99]." (PMID 38878676, 2024). "PKP3 performs an essential function in the prostate cancer tumor microenvironment by regulating invasion of the cell and tumor formation through the MMP7 protein." (PMID 37760912, 2023).
prostate carcinoma (continued). "In prostate cancer, IL-17 promoted prostate carcinogenesis through the induction of epithelial-to-mesenchymal transition mediated by MMP7." (PMID 35783266, 2022). "IL-17 stimulates MMP7 expression in prostate cancer to destroy the E-cadherin/β-catenin complex and release -catenin, hence promoting EMT and tumor cell invasion." (PMID 36339551, 2022). "We also relate its expression to the androgen receptor and MMP-7 protein, both critical to prostate cancer pathogenesis." (PMID 35201496, 2021). "ARF has been previously shown to stabilize the epithelial-to-mesenchymal transition (EMT) marker SLUG in prostate cancer, while it also regulates the tumor microenvironment through matrix metalloproteinase-7 (MMP7) nuclear translocation." (PMID 33445626, 2021). "Perlecan fragments in the serum of prostate cancer patients were correlated with overall MMP-7 staining levels in prostate cancer tissues." (PMID 32351878, 2020). "They proved that MMP-7 in the tumor-bone microenvironment was an important mediator of prostate cancer-induced osteolysis." (PMID 32751899, 2020). "Matrix metalloproteinase 7 (MMP7) plays essential role in prostate cancer cell invasion and epithelial to mesenchymal transition by breaking down extracellular matrix of tumor cells." (PMID 31671654, 2019). "Perlecan and MMP-7 co-localize at tissue boundaries when surveyed in prostate cancer sections, with MMP-7 proposed to act as a molecular switch by altering cancer cell behavior to favor cell dispersion and invasiveness." (PMID 32010611, 2019). "MMP7 is required to mediate cancer cell invasion and has been reported to promote prostate cancer progression through induction of epithelial-to-mesenchymal transition (EMT)." (PMID 31317026, 2019). "Collectively, these data suggested that Eya2 functions as a promoter for prostate cancer invasion, possibly by regulating MMP7." (PMID 31317026, 2019). "We also determined if polymorphisms in several Zn-dependent genes (MT2A, MMP-1, MMP-2, MMP-7, MMP-13) contributed to prostate cancer risk." (PMID 30036379, 2018). "In vitro study on prostate cancer cells showed that MMP-7 gene transcription is significantly upregulated in human prostate tumours comparing to normal tissue." (PMID 30036379, 2018). "A recent report suggested that IL‐17A promotes prostate cancer via MMP7‐induced EMT, which further supports the regulation of EMT by IL‐17A." (PMID 29689643, 2018). "In this study we sought to analyze to what extent variations in serum Zn level and polymorphisms in MT2A, MMP-1, MMP-2, MMP-7 and MMP-13 are related to prostate cancer among Polish men." (PMID 30036379, 2018). "The present study suggests a distinct difference in the response of myeloma to host-derived MMP-7, as compared to breast and prostate cancer." (PMID 28241871, 2017). "Previously, host derived MMP-7 has been shown to promote the growth of bone metastatic breast and prostate cancer." (PMID 28241871, 2017). "Host derived MMP-7 has previously been shown to support the growth of bone metastatic breast and prostate cancer." (PMID 28241871, 2017). "MMP7 has been shown to be overexpressed in prostate cancer tissue when compared to normal tissue and was recently demonstrated to be regulated by the ETV1 transcription factor." (PMID 25658610, 2015). "Additional functional studies to examine the potential role of allele-specific transcriptional regulation of MMP7 by rs11568818 and ETV1 for prostate cancer should be conducted." (PMID 25658610, 2015). "Taken together, these data strongly suggest a functional role for rs11568818 in the transcriptional regulation of the MMP7 gene for prostate cancer." (PMID 25658610, 2015). "HES6 knockdown influenced the expression of two cell migration-associated genes—metalloproteinase 7 (MMP7) and ITGB2 —as well as STEAP4, which was previously implicated in prostate cancer cellular proliferation." (PMID 25864518, 2015).
prostate carcinoma (continued). "In prostate cancer, 77% and 50% of prostate tumors were found to focally express MMP-7 by in situ hybridization analyses and western blotting, respectively." (PMID 24978435, 2014). "It was reported that the ETS family transcription factors, E1AF and ETV1 (ETS-related 81), increased expression of MMP-7 and contributed to tumor aggression of prostate cancer." (PMID 24978435, 2014). "In contrast, it was reported that perlecan interacts with a complex of sema3A, plexin-A1, and NRP-1 on the cell surface of prostate cancer cells and that cleavage of this complex by MMP-7 cell-cell bonds promotes the metastatic dissemination of prostate cancer cells." (PMID 37627074, 2023). "Furthermore, comparing the gene expression patterns between the central tumour region and tumour bone interface in prostate cancer bone metastases revealed MMP-7 as one of the most strongly upregulated genes at the tumour–bone interface." (PMID 35327500, 2022). "Additionally, MMP-7 promotes prostate cancer-induced osteolysis via the solubilization of the receptor activator of nuclear factor-kappaB (RANKL)." (PMID 35011011, 2021). "MMP7 participates in the development of multiple malignant tumors and is associated with the invasion and metastasis of cancers, including CRC, lung cancer, pancreatic cancer, tongue squamous cell carcinoma and prostate cancer." (PMID 35155451, 2021). "However, IL-17 was found to promote prostate cancer in mice and human cell lines by inducing the epithelial to mesenchymal transition via matrix metalloproteinase-7 (MMP-7)." (PMID 32552802, 2020). "In addition to the digestive tract and ovaries, the importance of MMP-7 for prostate cancer has also been proven." (PMID 32751899, 2020). "Moreover, analyses in rat models of prostate cancer revealed that MMP-7 is upregulated during carcinogenesis." (PMID 30036379, 2018). "Our result supports the observations about the role of MMP-7 in prostate cancer development." (PMID 30036379, 2018). "MMP-7: Epithelial cells in primary human prostate cancer express elevated levels of MMP-7." (PMID 24978435, 2014). "Overexpression MMP-7 promotes invasion of prostate cancer cells." (PMID 21629786, 2011). "Among them, MMP-2, MMP-9 and MMP-7 play a critical role in prostate cancer progression." (PMID 21629786, 2011). "In fact, in the bone metastatic setting, RANKL expression is boosted by prostate cancer cells through the expression of parathyroid hormone-related protein (PTHrP), and in parallel, bone resorption is modified by the expression of matrix metalloproteinase-7 (MMP7) by osteoclasts." (PMID 33535541, 2021). "It promotes invasion in hepatocellular carcinoma and epithelial–mesenchymal transition (EMT) in prostate cancer via MMP-2, MMP-7, MMP-9, and NF-κB signaling." (PMID 39205642, 2024). "MMP-7 and MMP-9 are known to be markers of prostate cancer invasion, and we observed elevated expression of these proteins." (PMID 38511770, 2024). "In prostate cancer, their roles have been discussed in a recent systematic-like review, where special emphasis is placed on MMP2, MMP7, and MMP9 since they are the most studied and most often positively correlated with prostate cancer tumorigenicity." (PMID 38255186, 2023). "But in a solid tumor, the IL-7/IL-7R axis promoted prostate cancer cell invasion and migration by activating the AKT/NF-κB pathway and increasing MMP-3 and MMP-7 expression." (PMID 31915416, 2019). "Thereafter, increased mRNA levels of MMPs were reported in TCDD-treated human cells, such as, MMP1 in keratinocytes and melanoma cells, MMP2 in melanoma cells, MMP3 and MMP7 in endometrial cells, and MMP9 in prostate cancer cells and melanoma cells." (PMID 16704738, 2006). "However, several studies have shown that factors such as MMP-7, Runx2, and CTGF can alter osteosclerotic bone metastasis to an osteolytic phenotype in prostate cancers." (PMID 33549040, 2021).